SMIM7 (small integral membrane protein 7)
Synonyms: C19orf42; MGC2747
Tractability: Antibody: UniProt predicts a signal peptide or a membrane-spanning region. PROTAC: ubiquitination databases record sites on it.
Gene: Protein-coding gene on chromosome 19 (16,630,751 to 16,660,442, reverse strand). Ensembl gene ENSG00000214046.
Subcellular location: Membrane
Subcellular location (Human Protein Atlas): Golgi apparatus
Gene Ontology:
Cellular component: membrane
Genetic constraint (gnomAD): Loss-of-function variants: 12 observed, 14.17 expected, observed/expected ratio (o/e) 0.85, 90% interval 0.54 to 1.37. The upper end of that interval is the gene's LOEUF score, 1.37, which puts it in group 5 of 6, group 1 being the genes least tolerant of losing a copy. Missense variants: 114 observed, 100.99 expected, observed/expected ratio (o/e) 1.13, 90% interval 0.97 to 1.32. Synonymous variants: 36 observed, 37.62 expected, observed/expected ratio (o/e) 0.96, 90% interval 0.73 to 1.26.
Homologues: Orthologues: rat Smim7 (97% identical), chimpanzee SMIM7 (96% identical), guinea pig SMIM7 (96% identical), mouse Smim7 (96% identical), pig SMIM7 (96% identical), rabbit SMIM7 (95% identical), tropical clawed frog smim7 (87% identical), zebrafish smim7 (87% identical), Caenorhabditis elegans Y51H7C.41 (52% identical).
Diseases named in the same sentence as SMIM7 in open-access papers:
SMIM7 is named in the same sentence as 2 diseases in open-access papers, as found by Europe PMC text mining. Sharing a sentence is not in itself a finding about the gene and the disease.
SMIM7 shares sentences with these, for which no sentence is quoted: infection (1 paper); liver cancer (1).